PIWIL2 (piwi like RNA-mediated gene silencing 2)
Diseases named in the same sentence as PIWIL2 in open-access papers (continued):
Sharing a sentence is not in itself a finding about the gene and the disease.
Pancreatic Cancer (2 papers, 2019 to 2020). "Further analysis revealed that PIWIL1 and PIWIL2, at both mRNA and protein expression levels, correlated positively with factors associated to the progenitor molecular subtype of pancreatic cancer." (PMID 31443431, 2019). "Given our previous results related to patient outcome, we wonder whether PIWIL1 or PIWIL2 would be associated to any of the four described molecular subtypes of pancreatic cancer." (PMID 31443431, 2019). "PIWIL1 and PIWIL2 have been recently evaluated in pancreatic cancer, and elevated expression of PIWIL2 conferred longer survival to patients." (PMID 32357464, 2020). "Then, mRNA expression of the most significant factors associated with each molecular subtype of pancreatic cancer of 186 pancreatic cancer patients from a TGCA dataset was correlated with PIWIL1 or PIWIL2 mRNA expression levels." (PMID 31443431, 2019). "On the other hand, the results presented here support the role of PIWIL2 protein expression as a prognostic biomarker in pancreatic cancer, and suggest a link between PIWIL2 expression and the progenitor molecular subtype of pancreatic cancer." (PMID 31443431, 2019). "This study shows the differential role of PIWIL1 and PIWIL2 in pancreatic cancer." (PMID 31443431, 2019). "Based on these findings, PIWIL1 and PIWIL2 expression may be considered a potential prognostic biomarker for resectable pancreatic cancer and may serve to guide subsequent adjuvant treatment decisions." (PMID 31443431, 2019). "In order to compare the potential prognosis value of PIWIL2 expression with the other clinical variables, we performed a Cox proportional hazards model for both progression-free and overall survival of patients with only pancreatic tumor origin." (PMID 31443431, 2019). "In the present study, we evaluated PIWIL1, PIWIL2, PIWIL3 and PIWIL4 expression in pancreatic cancer-derived cell lines and in one non-tumor cell line as healthy control." (PMID 32357464, 2020).
squamous cell carcinoma (2 papers, 2020 to 2021). A carcinoma arising from squamous epithelial cells. "In addition, PIWIL-2 was expressed in human endothelial cells [HUVECs (3/3) and HDMECs (1/1)], but not in the autonomously growing squamous cell carcinoma cell line A431 (0/2) (data not shown)." (PMID 32166374, 2020). "Similarly, there was no upregulation of PIWIL-2 in squamous cell carcinomas." (PMID 32166374, 2020).
atypical ductal hyperplasia (1 paper, 2020). Atypical ductal hyperplasia is an atypical proliferative lesion that falls in between the continuum from normal hyperplasia to low grade ductal carcinoma in situ. "PIWIL2 and PIWIL4 were downregulated in pre-invasive breast lesions such as atypical ductal hyperplasia (PIWIL2 (30%) and PIWIL4 (20%)) and ductal carcinoma in situ (PIWIL2 (40%) and PIWIL4 (40%))." (PMID 33008024, 2020).
basal cell carcinoma (1 paper, 2020). A carcinoma involving the basal cells. "We investigated the expression of PIWIL-2 in 9 basal cell carcinomas." (PMID 32166374, 2020).
benign ovarian tumors (1 paper, 2014). "In order to investigate a possible role of this pathway in EOC, we performed semi-quantitative RT-PCR to investigate the expression of PIWIL1, PIWIL2, PIWIL3, PIWIL4 and MAEL in advanced stage serous EOC (n = 25), benign ovarian tumors (n = 19) and normal ovarian tissue (n = 8)." (PMID 24932571, 2014).
cervical squamous intraepithelial lesions (1 paper, 2024). "When PIWIL2 expression is restored via heterogeneous integration of human papillomavirus, cellular reprogramming is initiated to form tumor‐initiating cells (TICs), which triggers cervical squamous intraepithelial lesions (SIL)." (PMID 39499767, 2024).
cervical tumor (1 paper, 2018). "We analyzed the expression of PIWIL2 and HDAC3 by tissue microarray containing 30 pairs of cervical tumor tissues and adjacent normal tissues, and found that both PIWIL2 and HDAC3 were more highly expressed in tumor tissues than those in adjacent tissues." (PMID 29555935, 2018).
colitis (1 paper, 2025). Inflammation of the colon. "Our database examination also showed that PIWIL2 is downregulated in samples from patients with ulcerative colitis, which highlights a gap in current research, since the PIWI pathway has not been previously studied in colitis and in inflammatory bowel disease." (PMID 40789164, 2025).
colon adenocarcinoma (1 paper, 2025). "Our results also show that the pathway experiences significant allelic losses and its expression is downregulated in colon adenocarcinoma, with PIWIL2 having the highest percentage of deletions and allelic losses within the pathway." (PMID 40789164, 2025).
colorectal adenocarcinoma (1 paper, 2025). The most common type of colorectal carcinoma. "PIWIL2 bound with piRNA-54265 to activate the STAT3 pathway and then promoted cell proliferation in colorectal adenocarcinoma." (PMID 41154843, 2025).
COVID-19 (1 paper, 2026). A disease caused by infection with severe acute respiratory syndrome coronavirus 2. "Transcriptomic profiling of peripheral blood mononuclear cells (PBMCs) from COVID-19 patients validated proxitropic variants (rs8192330 and rs4800403) with distinct expression signatures and prioritized DMTN and PIWIL2 as the likely causal genes." (PMID 42123708, 2026). "In conclusion, we identified shared genetic components for COVID-19 and CAD and prioritized DMTN and PIWIL2 as the likely causal genes for the observed shared genetic risk." (PMID 42123708, 2026).
ductal carcinoma in situ (1 paper, 2020). "We observed progressive PIWIL2 and PIWIL4 downregulation with absence or very slight nuclear staining (HScore = 0–0.5) in atypical ductal hyperplasia (PIWIL2 (30%, n = 3) and PIWIL4 (20%, n = 2)) and ductal carcinoma in situ (PIWIL2 (40%, n = 4) and PIWIL4 (40%, n = 4))." (PMID 33008024, 2020).
embryonic tumors (1 paper, 2023). "Our research group successfully constructed cancer stem cell-like cells named Piwil2-iCSCs by reprogramming human preputial fibroblasts (FBs) with the PIWIL2 gene in the early stage, and Piwil2-iCSCs were confirmed to induce the formation of embryonic tumors." (PMID 37941038, 2023).
glioblastoma (1 paper, 2025). The most malignant astrocytic tumor (WHO grade IV). "For example, PIWIL2 upregulation promotes glioblastoma cell proliferation and migration, and its level has been correlated with poor prognosis." (PMID 39849644, 2025).
liver cancer (1 paper, 2025). An epithelial or non-epithelial malignant neoplasm that arises from the liver. "In agreement, we demonstrated that tPIWIL2, like WT PIWIL2, enhances proliferation, invasion, and migration of liver cancer cells (HepG2 and Huh7)." (PMID 41422314, 2025). "Using liver cancer cell lines (Huh7, HepG2, SNU449, SNU398) overexpressing PIWIL2, we assessed peptide efficacy through cell viability and sphere formation assays." (PMID 41422314, 2025).
mesenchymal tumors (1 paper, 2017). "All the PIWIL2-GFP fibroblasts derived tumors tested stained positive for the transfected gene, PIWIL2, as well as VIMENTIN (marker of mesenchymal tumors), Synaptophysin (SYN, markers of neurogenic tumors) and NESTIN." (PMID 28103575, 2017).
metastatic cancers (1 paper, 2010). A carcinoma which has spread from the original site of growth to another anatomic site. "Consistent with the observations from cancer cell lines, PL2L proteins were also predominantly expressed in primary and metastatic cancers; whereas Piwil2 were essentially undetectable except in some apoptotic or apoptosing cells." (PMID 20975993, 2010). "The results suggest that Piwil2 is mainly expressed in apoptotic or apoptosing tumor cells, whereas PL2L proteins were expressed in euchromatin-enriched proliferating and metastatic cancer cells." (PMID 20975993, 2010). "Therefore, the “Piwil2” transcripts amplified by primers within PL2L genes and the translated proteins detected by mAbs Kao2/3, de facto represent PL2L genes and PL2L proteins in cancer cell lines or in the tissues of primary and metastatic cancers." (PMID 20975993, 2010).
mucinous adenocarcinoma (1 paper, 2025). An invasive adenocarcinoma composed of malignant glandular cells which contain intracytoplasmic mucin.
ovarian tumors (1 paper, 2023). "Lower levels of mRNA expression of genes of the 21 CTAs in ovarian tumors were detected for CTAG1A, CTAG1B, MAGEC1, and PIWIL2." (PMID 37835834, 2023).
Sotos syndrome (1 paper, 2017). Sotos syndrome is a rare multisystemic genetic disorder characterized by a typical facial appearance, overgrowth of the body in early life with macrocephaly, and mild to severe intellectual disability. "PIWIL2 is among 31 genes that were hypomethylated in HNSC, LUSC, and Sotos syndrome, raising the intriguing possibility that genes and pathways that are responsible for overgrowth and cancer susceptibility in Sotos syndrome also promote growth in sporadic cancers." (PMID 29213088, 2017).
teratoma (1 paper, 2014). A non-seminomatous germ cell tumor characterized by the presence of various tissues which correspond to the different germinal layers (endoderm, mesoderm, and ectoderm). "We also performed Western blotting with a sample of testis and its adjacent tumor (teratoma) to show that 14–16ex PIWIL2 antibody is able to detect the full-length PIWIL2 protein." (PMID 25384072, 2014). "Furthermore, RT-PCR with cDNA from normal testis, teratoma, TERA1 and NT2/D1 cell lines confirmed the absence of mRNA for the full-length PIWIL2 in all samples except testis." (PMID 25384072, 2014).
testicular cancer (1 paper, 2014). A primary or metastatic malignant neoplasm that affects the testis. "Further, using RACE experiments and promoter activity luciferase assay, we ascertained and validated the promoter regions for PIWIL2 isoforms in testicular cancer cell lines: for PL2L60A upstream of exon 5 in TERA1 and for PL2L80A upstream of exon 7 in NT2/D1." (PMID 25384072, 2014). "Finally, we established alternative transcription start and polyadenylation sites for PIWIL2 short isoforms in testicular cancer cell lines." (PMID 25384072, 2014).
tuberculosis (1 paper, 2024). A chronic, recurrent infection caused by the bacterium Mycobacterium tuberculosis. "In tuberculosis (TB), the increased activity of PIWIL2 and PIWIL4, along with the significant presence of piRNAs such as piRNA-1007467, piR-hsa-1344, and piR-hsa-1944, highlights the complex involvement of the piRNA-PIWI axis in TB development." (PMID 39717847, 2024).
ulcerative colitis (1 paper, 2025). An inflammatory bowel disease involving the mucosal surface of the large intestine and rectum. "This analysis showed that out of all the members of the PIWI-piRNA pathway that were queried, PIWIL2 was the gene that was more predominantly downregulated in ulcerative colitis." (PMID 40789164, 2025).
cancer (57 papers, 2010 to 2025). A tumor composed of atypical neoplastic, often pleomorphic cells that invade other tissues. "Changes in expression, such as overexpression (e.g., PIWIL1) or downregulation (e.g., PIWIL2), has been identified in several cancers and are associated with poor prognosis." (PMID 40949873, 2025). "Similar to PIWIL1, several studies have indicated an association between PIWIL2 and cancer cell stemness." (PMID 38303021, 2024). "Recently, we found that PIWIL2, a novel cancer testis protein, is highly expressed in ESCC and associated with high T-stage and poor 5-year survival rate in patients." (PMID 33469229, 2021). "In most of malignant tumors belonging to this panel, we observed an expression profile comparable to IBCs associating variable PIWIL2 and PIWIL4 genes downregulation and an emerging aberrant expression of PIWIL1 and PIWIL3." (PMID 33008024, 2020). "In this study, we aimed to assess an association between PIWIL1 and PIWIL2 expression and the prognosis of biliopancreatic cancer patients." (PMID 31443431, 2019). "In this context, an aberrant expression of PIWIL1 and PIWIL2 have been associated with different types of cancer and showed a variable prognostic and diagnostic potential." (PMID 31443431, 2019). "The reduced stabilization and phosphorylation of HDAC3 caused by PIWIL2 knockdown inhibits cancer cell proliferation and increases cancer cell apoptosis." (PMID 29555935, 2018). "So we are curious about whether PIWIL2 exerted a role in cancer through an association with epigenetic factors." (PMID 29555935, 2018). "Furthermore, in this study, we demonstrated that E6 and E7 restored Piwil2 expression, sequentially reactivated gene sets associated with cancer stem-like cell identity, and induced TIC formation." (PMID 27602489, 2016). "First, we detected the possible changes in cancer-associated characteristics caused by Piwil2." (PMID 27602489, 2016). "Although our results in this study overall support a tumor suppressing role for PIWIL2 in colon tumorigenesis, there have been conflicting reports regarding the role of PIWIL2 in cancer." (PMID 40789164, 2025). "Aberrant PIWIL2 expression has been implicated in promoting proliferation in HCC and other cancers, with its tumorigenic functions mediated through interactions with HDAC3, NME2, β-catenin (CTNNB1), and others via the PIWI and MID domains." (PMID 41422314, 2025). "Previous in vitro work studying PIWIL2 has been primarily conducted in transformed cancer cell lines, or in commonly used cell lines such as HEK-293 cells, none of which are representative of the normal differentiated epithelium." (PMID 40789164, 2025). "Nevertheless, reduced PIWIL2 expression correlates positively with increased overall survival across multiple cancer types, suggesting its potential as a general prognostic indicator." (PMID 40725379, 2025). "Among the four PIWI proteins expressed in humans, PIWIL1 and PIWIL2 seem to be the most promising candidates to be prognostic biomarkers in cancer." (PMID 38303021, 2024). "Inhibition of PAK1 phosphorylation of TBCB by PIWIL2 can lead to increased migration and invasion of cancer cells." (PMID 39596284, 2024). "The findings also reveal that DEX promotes EMT, a process critical for cancer metastasis, by upregulating PIWIL2." (PMID 39596284, 2024). "Upon overexpression of PIWIL2 in fibroblasts, the cells acquired several characteristics of cancer stem-like cells and upregulated the expression of several piRNAs including piRNA MW557525." (PMID 38303021, 2024). "In summary, PIWIL2 is expressed in several cancer types, however, data on its possible use as a biomarker are currently limited." (PMID 38303021, 2024). "Based on this, our research group constructed a cancer-like stem cell model, Piwil2-iCSCs, by reprogramming FBs with the PIWIL2 gene and confirmed that these cells can induce embryonic-derived tumors." (PMID 37941038, 2023).
cancer (continued). "“Ribosome” and “Spliceosome” were the top terms among upregulated genes in the KEGG pathway analysis; whereas, cancer‐related terms were common among the downregulated pathways, in agreement with the known oncogenic role of Piwil2 in various human tumors." (PMID 36472244, 2023). "The human genome encodes four PIWIL genes, known as PIWIL1 (HIWI), PIWIL2 (HILI), PIWIL3 (HIWI3), and PIWIL4 (HIWI2); some of which were found to be highly expressed in several human cancers." (PMID 32204558, 2020). "Similar experiments involving transfection of fibroblasts with the testis specific human PIWIL2 gene have previously demonstrated transformation into a cancer stem cell like phenotype." (PMID 33330072, 2020). "PIWIL2 staining was identified in the nucleus of cancer cells with a slight intensity (HScore: 0.5–1)." (PMID 33008024, 2020). "Since PIWIL-2 is known to play a role in the maintenance of germline stem cells as well as in the development of carcinomas, we set out to look for a possible role of this protein and piRNAs in the skin." (PMID 32166374, 2020). "PIWIL-2 overexpression has been reported to play a critical role in the development of a variety of carcinomas." (PMID 32166374, 2020). "PIWIL2 is up-regulated both at the RNA and protein level in malignant cancer tissues in NSCLC compared with adjacent normal tissue." (PMID 31399034, 2019). "Emerging roles of PIWIL2 in cancer showed that PIWIL2 is involved in the proliferation, apoptosis, and migration of cancer cell." (PMID 29555935, 2018). "Our present study firstly revealed that PIWIL2 can play a role in HDAC3-mediated epigenetic regulation on cancer cell proliferation and apoptosis." (PMID 29555935, 2018). "Previous studies indicated that PIWIL2 is expressed not only in germ cells but also in cancer cells, playing important roles in tumorigenesis." (PMID 28903391, 2017). "It is likely that PIWIL2 is a key gene involved in the initiation, development and maintenance of human cancers." (PMID 28103575, 2017). "CSC-like cells obtained using human fibroblasts with a single transcription factor Piwil2 (unpublished) were called Piwil2-induced cancer stem cells (Piwil2-iCSC)." (PMID 27894076, 2017). "In adult tissues PIWIL2 is silenced in both somatic and stem cells, but is widely expressed in most types of cancers." (PMID 28103575, 2017). "Taken together, our work described a novel funtion for the cancer/testis antigen PIWIL2 in regulation of the circadian clock, providing a molecular link between spermatogenesis as well as tumorigenesis to the dysfunction of circadian rhythms." (PMID 28903391, 2017). "Recently it has been demonstrated that transfection of mouse embryonic fibroblasts with a full length cDNA copy of the mouse PIWIL2 gene produced cancer stem cell like cell lines in vitro." (PMID 28103575, 2017). "We have found that while PIWIL2 is mainly detected in apoptotic cells of primary cancers, PL2L60, a variant of PIWIL2, is widely expressed in various types of proliferating cancer cells, promoting tumor growth." (PMID 28545024, 2017). "As we have shown that PIWIL2 regulates circadian proteins in cancer cells as well as mammal germ cells." (PMID 28903391, 2017). "Transfected PIWIL2-GFP fibroblasts exhibit multiple characteristics associated with cells capable of initiating and maintaining cancers." (PMID 28103575, 2017). "Our results showed that PIWIL2 can significantly up-regulate phosphorylation level at Ser9 of GSK3β in germ cells and cancer cells." (PMID 28903391, 2017). "Here we report that the cancer/testis antigen PIWIL2 can repress circadian rhythms both in the testis and cancer cells." (PMID 28903391, 2017). "The positive expression rate of Piwil2 in the nuclear part of carcinoma tissue was 100% (86/86), significantly higher than that in the cytoplasm [47.67% (41/86)] (Fisher exact test, P = 0.000)." (PMID 27894076, 2017).